ABCA3 (ATP binding cassette subfamily A member 3)
Description:
Catalyzes the ATP-dependent transport of phospholipids such as phosphatidylcholine and phosphoglycerol from the cytoplasm into the lumen side of lamellar bodies, in turn participates in the lamellar bodies biogenesis and homeostasis of pulmonary surfactant. Transports preferentially phosphatidylcholine containing short acyl chains. In addition plays a role as an efflux transporter of miltefosine across macrophage membranes and free cholesterol (FC) through intralumenal vesicles by removing FC from the cell as a component of surfactant and protects cells from free cholesterol toxicity.
Synonyms: ABC3; ABC-C; EST111653; LBM180; SMDP3
Tractability: Small molecule: a structure with a bound ligand is known; it belongs to a druggable protein family. Antibody: its Gene Ontology location is reachable by antibodies, with high confidence; UniProt predicts a signal peptide or a membrane-spanning region. PROTAC: ubiquitination databases record sites on it; its protein half-life has been measured.
Gene: Protein-coding gene on chromosome 16 (2,275,878 to 2,340,749, reverse strand). Ensembl gene ENSG00000167972.
Subcellular location: Endosome, multivesicular body membrane; Cytoplasmic vesicle membrane; Late endosome membrane; Lysosome membrane
Subcellular location (Human Protein Atlas): Nucleoplasm; Vesicles
Pathways (Reactome):
Disease: Defective ABCA3 causes SMDP3
Metabolism of proteins: Surfactant metabolism
Transport of small molecules: ABC transporters in lipid homeostasis
Gene Ontology:
Molecular function: ABC-type xenobiotic transporter activity; ATP hydrolysis activity; ATPase-coupled intramembrane lipid transporter activity; phosphatidylcholine flippase activity; phosphatidylcholine transfer activity; ATPase-coupled transmembrane transporter activity; lipid transporter activity; ABC-type transporter activity; ATP binding
Biological process: phosphatidylcholine metabolic process; phospholipid transport; positive regulation of cholesterol efflux; positive regulation of phospholipid efflux; positive regulation of phospholipid transport; positive regulation of protein homooligomerization; regulation of phosphatidylcholine metabolic process; xenobiotic export from cell; xenobiotic transmembrane transport; xenobiotic transport; lipid transport; lung development; organelle assembly; phosphatidylglycerol metabolic process; response to xenobiotic stimulus; surfactant homeostasis; lipid translocation; phospholipid homeostasis; positive regulation of vesicle fusion; regulation of lipid biosynthetic process; regulation of lipid transport; response to glucocorticoid; transmembrane transport
Cellular component: alveolar lamellar body; alveolar lamellar body membrane; cytoplasmic vesicle membrane; extracellular region; lamellar body; lamellar body membrane; late endosome; late endosome membrane; lysosomal membrane; plasma membrane; cytoplasm; endomembrane system; membrane; multivesicular body membrane
Genetic constraint (gnomAD): Loss-of-function variants: 88 observed, 171.76 expected, observed/expected ratio (o/e) 0.51, 90% interval 0.43 to 0.61. The upper end of that interval is the gene's LOEUF score, 0.61, which puts it in group 2 of 6, group 1 being the genes least tolerant of losing a copy. Missense variants: 2,164 observed, 2,337.6 expected, observed/expected ratio (o/e) 0.93, 90% interval 0.89 to 0.96. Synonymous variants: 1,066 observed, 997.81 expected, observed/expected ratio (o/e) 1.07, 90% interval 1.01 to 1.12.
Gene-disease validity (ClinGen):
ClinGen rates the evidence that ABCA3 causes each of these diseases.
interstitial lung disease due to ABCA3 deficiency (autosomal recessive): Definitive.
Homologues: Orthologues: macaque ABCA3 (99% identical), chimpanzee ABCA3 (98% identical), guinea pig ABCA3 (90% identical), dog ABCA3 (89% identical), rabbit ABCA3 (88% identical), mouse Abca3 (88% identical), rat Abca3 (88% identical), pig ABCA3 (88% identical), tropical clawed frog abca3 (63% identical), zebrafish abca3b (63% identical), Drosophila melanogaster Abca3 (38% identical), Caenorhabditis elegans abt-4 (33% identical), and 10 more. Paralogues in human: ABCA1 (38% identical), ABCA4 (36% identical), ABCA2 (36% identical), ABCA7 (36% identical), ABCA13 (31% identical), ABCA12 (31% identical), ABCA9 (25% identical), ABCA8 (24% identical), ABCA6 (24% identical), ABCA5 (24% identical), ABCA10 (23% identical).
Diseases named in the same sentence as ABCA3 in open-access papers:
ABCA3 is named in the same sentence as 83 diseases in open-access papers, as found by Europe PMC text mining. Sharing a sentence is not in itself a finding about the gene and the disease. The quoted sentences say what the papers report.
lung disease (29 papers, 2005 to 2025). "The rarity and heterogeneity of lung disease due to ABCA3 variants raise significant challenges in recognition, diagnosis and management." (PMID 40746635, 2025). "Lung disease due to pathogenic variants in the adenosine triphosphate (ATP) binding cassette subfamily A member 3 (ABCA3) gene has been extensively described among infants and children but is rarely described in an adult population." (PMID 40746635, 2025). "Lung disease due to pathogenic variants in the ABCA3 gene has been extensively described among infants and children but is rarely described in an adult population." (PMID 40746635, 2025). "Pathogenic variants in genes associated with SFTPB and ABCA3 result in severe and often fatal lung diseases, typically inherited in an autosomal recessive manner." (PMID 38203821, 2024). "Fatal cases of ABCA3 deficiency were described in association with abnormal trafficking, while defects in phosphatidylcholine were correlated with less severe lung disease." (PMID 39457702, 2024). "Pathogenic variants in genes responsible for SFTPB and ABCA3 lead to severe and frequently fatal lung diseases, usually inherited in autosomal recessive patterns." (PMID 38203821, 2024). "ABCA3 has been pathologically linked to surfactant deficiency, a lung disorder relating to aberrant lipid transport that is fatal in newborns while there is very little knowledge on the physiological and pathological functions of ABCA9 and ABCA10." (PMID 36385764, 2022). "ABCA3 is expressed in a number of tissues, the only disease associated with biallelic variants is lung disease." (PMID 34715861, 2021). "ABCA3 is a crucial protein of pulmonary surfactant biosynthesis, associated with recessive pulmonary disorders such as neonatal respiratory distress and interstitial lung disease." (PMID 34638622, 2021). "ABCA3 is a lipid transporter located in the outer membrane of lamellar bodies in AT2 cells; mutations of the ABCA3 gene can disrupt pulmonary surfactant homeostasis and lead to inherited pulmonary diseases." (PMID 33156843, 2020). "Homozygous or compound heterozygous mutations of the ABCA3 gene are currently considered the etiological basis of severe neonatal lung diseases and symptoms of surfactant deficiency." (PMID 28642621, 2017). "Lung disease caused by ABCA3 mutations is an inherited autosomal recessive disorder, requiring mutations on both alleles." (PMID 24730976, 2014). "It is mainly expressed in the lungs at the limiting membrane of the lamellar bodies of alveolar type II cells; loss of normal ABCA3 function is associated with lung disease." (PMID 24730976, 2014). "The clinical spectrum and severity of lung disease caused by ABCA3 deficiency is extremely variable, strongly depending on the mutations found and the patho-morphological pattern induced." (PMID 24730976, 2014). "All three mutations were found in children with ABCA3-associated lung disease being either fatal neonatal respiratory distress syndrome (L101P and R43L) or chronic ILD (R280C; own unpublished data,)." (PMID 21214890, 2011). "In 2004 mutations of the ABCA3 gene were recognized as a cause of lung diseases in full-term neonates with fatal pulmonary surfactant deficiency." (PMID 21214890, 2011). "The consanguinity and a family historyof neonatal respiratory distress suggest that the lung disease associatedwith mutations in the ABCA3 gene were inherited in an autosomal-recessive manner." (PMID 15819986, 2005). "Lung disease due to ABCA3 variants is inherited in an autosomal recessive fashion." (PMID 40746635, 2025). "It was reported that heterozygosity for ABCA3 (another gene responsible for surfactant dysfunction) mutations modifies the severity of lung disease in individuals with the same SFTPC mutation suggesting modifier genes may be involved." (PMID 31462320, 2019). "The results presented here might pave the way for mutation‐group specific treatment of pulmonary diseases caused by ABCA3 mutations." (PMID 31210424, 2019).
lung disease (continued). "We show here that, like some other proteins of the lysosomal membrane, ABCA3 is a substrate of cathepsin L. Therefore, cathepsin L may represent a potential target to therapeutically influence ABCA3 activity in ABCA3-associated lung disease." (PMID 27031696, 2016). "To test this, we first screened 760 adults with extreme lung phenotypes in the Copenhagen City Heart Study to identify ABCA3 variants that could potentially be associated with lung disease in the general population." (PMID 22866751, 2012). "Given this, ABCA3 variants, and in particular E292V, could play an important role on development of common pulmonary disorders in the general population." (PMID 22866751, 2012). "A large number of ABCA3 variants may result in human lung disease." (PMID 37108718, 2023). "ABCA3 is a highly conserved multi-membrane-spanning protein belonging to the ATP-binding cassette transporter superfamily and that plays a critical role in maintaining pulmonary surfactant homeostasis, with mutations confirmed to contribute to lung diseases including lung cancer." (PMID 34368151, 2021). "Recessive mutations in the ABCA3 gene have been related to deficiency of pulmonary surfactant leading to neonatal lung disease and chronic lung disease in children; however, frequency of chronic lung disease due to ABCA3 mutations in the general population is unknown." (PMID 22866751, 2012). "ABCA3 dysfunction has also been shown to play a role in the development of pulmonary disorders such as neonatal respiratory distress and interstitial lung disease." (PMID 38275610, 2024). "The semi-quantitative sum responses to HCQ in vitro of the two ABCA3 variants were correlated to the respiratory outcomes of patients with ABCA3-related lung disease (Spearman’s r value 0.54." (PMID 37175887, 2023). "In the future, randomized controlled and prospective studies in children with ABCA3-related lung disease, in vivo drug level monitoring, and/or other personalized treatments based on advanced cellular models are expected." (PMID 37175887, 2023). "We identified 48 patients with ABCA3-related lung disease from the Kids Lung Register, of which 30 were treated with HCQ and had sufficient clinical records." (PMID 37175887, 2023). "Cell cultures derived from patients with ABCA-3 deficiency that reflect the genetic and phenotypic features of ABCA3-associated lung disease would provide a means to study disease mechanisms and investigate potential therapeutics." (PMID 35265641, 2022). "Both gene addition and gene editing strategies are compared to best design treatments for lung diseases resulting from pathogenic variants in the SFTPB, SFTPC, and ABCA3 genes." (PMID 35098209, 2021). "Mutations in human SFTPB (surfactant associated protein B), and ABCA3 (ATP-binding cassette, sub-family A (ABC1), member 3) genes cause severe lung disease in new-borns, often resulting in respiratory failure at birth." (PMID 22916088, 2012). "It is clear that ABCA3-related lung disease may be additionally affected by modifier genes or environmental factors, which are not easily explored in vitro." (PMID 37108718, 2023). "Newborns with monoallelic ABCA3 sequence variants may have an RDS phenotype at birth, particularly if born prematurely, but subsequently improve and even apparently resolve their lung disease." (PMID 33799761, 2021). "Even for ABCA3, which is clearly associated with development of various lung diseases, no specific treatment exists for disorders caused ABCA3 mutations." (PMID 35011607, 2021). "Functional impairment of ABCA3 due to mutations may lead to fatal or chronic disturbances of ATII cells and surfactant homoeostasis resulting in pulmonary diseases like neonatal respiratory distress syndrome and chronic interstitial lung disease." (PMID 31210424, 2019).
lung disease (continued). "Interfering with the activity of cathepsin L in alveolar epithelial type II cells may thus represent an approach to ameliorate ABCA3 function in patients suffering from lung disease due to ABCA3 haploinsufficiency." (PMID 27031696, 2016). "Similar as proposed for SP-C deficiency, intracellular stress and apoptosis of AECII might play a role in pathogenesis of ABCA3-related lung disease." (PMID 21214890, 2011). "Since there are no therapies known for the lung disease due to ABCA3 mutations, the majority of affected newborns die from respiratory failure in the neonatal period." (PMID 15819986, 2005). "Currently, no specific therapy exists for lung diseases related to pathogenic ABCA3 variants." (PMID 37175887, 2023). "ABCA3 may also act as a modifier gene for the phenotype associated with an SFTPC mutation, as heterozygosity for ABCA3 mutations in severely affected infants with SFTPCI73T leads to more severe lung disease than family members with only the I73T mutation." (PMID 24730976, 2014). "The ABCA3 G964D mutation identified in our patients has never been described previously and it shows an autosomal recessive pattern of inheritance, as suggested by evidence that lung disease develops only in homozygous carriers." (PMID 24730976, 2014). "Except for one patient, the phenotype of non-fatal lung disease caused by ABCA3 mutations is unknown and requires screening for ABCA3 mutations in neonates and children with severe ILD where no underlying cause can be found." (PMID 15819986, 2005). "Thus, current therapies for patients with lung disease due to ABCA3 mutations are nonspecific and ineffective, with the only known definitive treatment option being lung transplant, as was the case for the children homozygous for E690K or W308R ABCA3 mutations profiled in our studies." (PMID 38226623, 2024). "The exact amount of functional ABCA3 needed to prevent lung disease is not known." (PMID 33799761, 2021). "As ABCA3 expression may continue to increase with maturity, such infants usually recover from their lung disease, although this has not been formally studied." (PMID 33799761, 2021).
interstitial lung disease (28 papers, 2011 to 2025). A diverse group of lung diseases that affect the lung parenchyma. "The pathogenic variants in ABCA3 are the most frequent monogenetic cause for interstitial lung disease in children (chILD) associated with surfactant dysfunction." (PMID 37175887, 2023). "Biallelic mutations of ABCA3 has been associated with fatal respiratory distress syndrome and interstitial lung disease (ILD) in children." (PMID 28642621, 2017). "Mutations in the ABCA3 gene cause respiratory distress syndrome in new-borns and childhood interstitial lung disease." (PMID 27031696, 2016). "Abca3 mutations are responsible for fatal surfactant deficiency and interstitial lung disease." (PMID 38970705, 2024). "Mutations in ATP-binding cassette A3 (ABCA3), a phospholipid transporter critical for surfactant homeostasis in pulmonary alveolar type II epithelial cells (AEC2s), are the most common genetic causes of childhood interstitial lung disease (chILD)." (PMID 38226623, 2024). "Pathogenic variants in the gene for lipid transporter ATP-binding cassette subfamily A member 3 (ABCA3) are the most prevalent known monogenic cause for neonatal surfactant dysfunction syndrome and interstitial lung disease in children (chILD) and young adults." (PMID 37108718, 2023). "Biallelic variants in ABCA3, the gene encoding the lipid transporter ATP-binding cassette subfamily A member 3 (ABCA3) that is predominantly expressed in alveolar type II cells, may cause interstitial lung diseases in children (chILD) and adults." (PMID 37175887, 2023). "Patients with bi-allelic variants in ABCA3 may suffer from a variable severity of interstitial lung disease." (PMID 37108718, 2023). "We found that the heterozygous ABCA3 gene variants may contribute to susceptibility to interstitial lung diseases in the Chinese population." (PMID 28642621, 2017). "Mutations of the ABCA3 gene lead to fatal neonatal surfactant deficiency and chronic interstitial lung disease (ILD) of children." (PMID 21214890, 2011). "Today ABCA3 mutations are known to cause also chronic interstitial lung disease (ILD) in children and older patients." (PMID 21214890, 2011). "Furthermore, pathogenic variants of SFTPC and some of the ABCA3 genes are recessive and dominantly inherited and have been linked to chronic interstitial lung disease (ILD) in term newborns, children, and adults." (PMID 38203821, 2024). "In-frame insertions/deletions or missense ABCA3 variants may result in “hypomorphic” variants, which may be compatible with survival and associated with chronic interstitial lung disease (ILD) in children and adults." (PMID 37175887, 2023). "Heterozygous SFTPC mutations concomitant, as well as heterozygous mutations in ATP-binding cassette transporter A3 (ABCA3) in infants with interstitial lung diseases (ILD), might likely led to development of clinical ILD." (PMID 35939165, 2022). "We describe the clinical course of a patient over 39 years and her younger brother who were both diagnosed at birth with an unspecified paediatric interstitial lung disease (ILD) and were eventually diagnosed with ABCA3 mutation in their adulthood." (PMID 32782805, 2020). "Mutations causing misfolding and mistrafficking of SFTPA/B/C and ABCA3 activate UPR and cause AT2 cell injury and interstitial lung disease in newborn infants and adults." (PMID 30604742, 2019). "Mutations in adenosine triphosphate-binding cassette transporter A3 (ABCA3) (OMIM: 601615) gene constitute the most frequent genetic cause of severe neonatal respiratory distress syndrome (RDS) and interstitial lung disease (ILD) in children." (PMID 31331098, 2019). "Mutations in SP-C, SP-D, and ABCA3 have been related to surfactant dysfunction and neonatal respiratory failure (NRF) in full-term babies and interstitial lung disease (ILD) in older children and adults." (PMID 27670912, 2016).